LAG3 (lymphocyte activating 3)
Diseases named in the same sentence as LAG3 in open-access papers (continued):
Sharing a sentence is not in itself a finding about the gene and the disease.
Autoimmunity (continued). "The studies in this paper indicate that LAG-3 plays a critical role in decreasing the manifestations of Hg-induced autoimmunity." (PMID 25122007, 2014). "Further, in LAG-3-deficient mice, mercury elicited higher amounts of IL-6, IL-4 and IFN-γ, cytokines known to play a critical role in mercury-induced autoimmunity." (PMID 25122007, 2014). "Our present study shows that LAG-3 exerts a critical regulatory role in a model of induced experimental autoimmunity." (PMID 25122007, 2014). "An agonistic anti-LAG3 antibody (IMP761) is currently under development for T cell–mediated autoimmunity, and this approach could have potential for clinical transplantation." (PMID 40359031, 2025). "LAG-3 expression in T lymphocytes is typically transient and appears in response to antigenic stimulation, suggesting that this receptor functions as a negative regulator that controls excessive immune activation and prevents autoimmunity." (PMID 40574024, 2025). "Conversely, in type 1 diabetes, the absence or insufficient expression of LAG-3 may lead to increased autoimmunity and destruction of pancreatic β cells." (PMID 40574024, 2025). "One possibility is that LAG3 may suppress autoimmunity by inhibiting autoreactive T cells recognizing stable autoantigen–MHC class II in the periphery that somehow escaped thymic negative selection." (PMID 38556085, 2024). "In contrast to PD-1 and CTLA-4, it has been determined that the loss of LAG-3 alone does not lead to the development of autoimmunity in non-autoimmune-prone mice." (PMID 38390331, 2024). "Their findings emphasized the significance of a LAG-3 agonist in the treatment of autoimmunity." (PMID 37946301, 2023). "As key and well-known regulatory immune checkpoint molecules, programmed death-1 (PD-1) as well as its ligand PD-L1 checkpoint pathway, in addition to immune checkpoint genes, including CTLA-4 and LAG3 play important roles in maintaining the balance between immune tolerance and autoimmunity." (PMID 35847354, 2022). "Lag3 is an inhibitory receptor that induces T cell exhaustion and suppresses excessive T cell responses that might induce autoimmunity." (PMID 33004854, 2020). "Interestingly, the superior tumor immunity provided by PI-3065 and anti-LAG3 combination treatment was accompanied by autoimmunity." (PMID 33093155, 2020). "CD4+CD49b+LAG3+ type 1 regulatory (Tr1) cells are important for controlling autoimmunity and could be involved." (PMID 30863412, 2019). "Another study revealed that LAG-3 acts synergistically with PD-1 to prevent autoimmunity in mice." (PMID 31134049, 2019). "Lymphocyte activation gene-3 (LAG-3, CD223) expressed on activated T, natural killer (NK) and B cells is a negative regulatory protein for T cell function implicated in preventing tissue damage and autoimmunity." (PMID 31554169, 2019). "Both PD-1 and LAG-3 play important roles during the normal immune response to prevent autoimmunity." (PMID 30619285, 2018). "Meanwhile, LAG-3 can effectively prevent the onset of autoimmune disorders." (PMID 30603054, 2018). "Immunological stimulation such as autoimmunity and vaccination may reduce the number of LAG3+ Tregs via costimulation." (PMID 28511719, 2017). "Therefore, in addition to PD-1, we analyzed the expression of the co-inhibitory receptors LAG-3 and Tim-3, which are known to play important roles in limiting autoimmunity, in CD4+ and CD8+ T cells." (PMID 28356069, 2017). "In addition, LAG-3 has been described also as a coinhibitory receptor repressing the T cell response in autoimmunity and cancer." (PMID 29209313, 2017). "Furthermore, LAG-3, another inhibitory co-receptor, has been shown to act synergistically with PD-1 to prevent autoimmunity." (PMID 27912762, 2016). "LAG-3 deficiency alone does not induce autoimmunity in non-autoimmune-prone mouse strains and does not induce major alterations in T cell development or function but a reduced NK cell cytotoxicity." (PMID 26347741, 2015).
Autoimmunity (continued). "Additionally, the lymphocyte activation gene-3 (LAG-3) is an important regulator of autoimmunity in response to mercury." (PMID 26064998, 2015). "Therefore, we conclude that LAG-3 exerts an important regulatory effect on autoimmunity elicited by a common environmental pollutant." (PMID 25122007, 2014). "The previous experiments show that LAG-3 can modulate the regulation of Hg-induced autoimmunity." (PMID 25122007, 2014). "Thus our data indicate that LAG-3 plays an important role in the prevention of environmentally-induced autoimmunity." (PMID 25122007, 2014). "However, in the case of mice bearing 4T1 tumors, LAG3 blockade in combination with PI-3065 resulted in the development of varying degrees of autoimmunity with all animals developing a starry coat and inflammation of the skin a week after commencing dual treatment." (PMID 33093155, 2020). "However, despite its incredible potential in treatment of cancer, autoimmunity, and infectious disease, much remains unknown about how LAG3 functions." (PMID 33488626, 2020). "Interestingly, similarly to the case of CD69, LAG3 deficiency does not result in basal lymphocyte dysfunction but rather impairs tolerogenic mechanisms upon antigen activation leading to exacerbated autoimmunity." (PMID 25880134, 2015). "Although both the expression and putative function of LAG-3 on B cells have to be confirmed, its role could be inhibitory as well and could represent an additional regulatory element in Hg-induced autoimmunity, a model which manifests itself essentially via humoral manifestations." (PMID 25122007, 2014). "Lymphocyte activation gene 3 (LAG-3), or CD223, is an inhibitory receptor that plays an important role in the prevention of autoimmunity." (PMID 40006675, 2025). "LAG-3 is known to play an important immunoregulatory role as a checkpoint inhibitory receptor (CIR) in cancer, but the function of LAG-3 in autoimmunity, and RA in particular, is only sparsely described." (PMID 37287025, 2023). "Expression of ICP such as: CTLA4, PD1, LAG3, and TIM3 regulates prolonged activation of T-cells by maintaining peripheral tolerance and preventing autoimmunity." (PMID 37104271, 2023). "LAG-3: Lymphocyte activation gene-3 (LAG-3, also known as CD223) is a checkpoint inhibitor, where it acts as an inhibitory co-receptor, playing pivotal roles in autoimmunity, tumor immunity, and anti-infection immunity." (PMID 33952230, 2021). "Lymphocyte activation gene 3 (LAG-3, CD223) is an immune checkpoint protein whose up-regulation prevents the onset of autoimmunity." (PMID 31207938, 2019). "Activation of co-inhibitory receptors, including CTLA-4, PD-1, LAG-3, TIM-3, and TIGIT, induce immune tolerance, therefore their stimulation would be beneficial in autoimmune disorders." (PMID 30564191, 2018). "These cells exert their regulatory functions via a number of unique surface regulatory molecules, including LAG3 and CD69, acting separately or synergistically to diminish inflammation, including Th17-driven autoimmunity." (PMID 25880134, 2015). "Increasing evidence suggest that LAG3 and PD1 independently regulate autoimmunity; while simultaneous inhibition of LAG3 and PD1 enhances anti-tumor immunity or leads to autoimmunity." (PMID 26318293, 2015). "The immune co-inhibitory receptors lymphocyte activation gene-3 (LAG3) and programmed cell death 1 (PD1) synergistically contribute to autoimmunity and tumor evasion." (PMID 26318293, 2015). "Although the immunomodulatory potential of LAG3 is being explored in cancer and autoimmunity, there is no information on its role after organ transplantation." (PMID 40359031, 2025). "Lymphocyte activation gene 3 (LAG-3) is another checkpoint target that is expressed on activated T cells 3–4 days post-activation, where it suppresses T cell activation and prevents autoimmunity." (PMID 39337605, 2024).
Autoimmunity (continued). "Although genetic deletion of LAG3 alone did not induce spontaneous autoimmunity, mice with both LAG3 and PD1 deleted experienced more severe multiple organ failure than mice with only PD1 deleted, suggesting that LAG3 and PD1 act synergistically." (PMID 38556085, 2024). "Furthermore, LAG‐3 function was also reported to ameliorate experimental autoimmune encephalomyelitis (EAE) and environmentally induced autoimmunity." (PMID 39560030, 2024). "Lymphocyte-activating gene 3 (LAG-3) describes a cell surface receptor expressed by T cells, which serves as an inhibitory checkpoint regulator during the interaction with MHC II molecules to prevent autoimmunity." (PMID 37958298, 2023). "LAG-3 is often co-expressed with PD-1 and it has a negative regulatory effect over T-cell function, preventing tissue damage and autoimmunity." (PMID 36612271, 2022). "Lag3 loss on intra-islet non-obese diabetic CD8 T cells accelerates autoimmune diabetes and highlights Lag3 T cell inhibition differences between autoimmunity, cancer and infection." (PMID 36314014, 2022). "Mice with the single knockout of LAG-3 do not develop any autoimmune disorders within the first year after birth." (PMID 33968036, 2021). "Beyond the inhibitory activity of LAG-3 on different types of lymphocytes, LAG-3 may also be necessary to negativelyregulate autoimmunity in many disease-prone environments." (PMID 30603054, 2018). "Co-inhibitory receptors, including cytotoxic T-lymphocyte associated protein 4 (CTLA-4), programmed cell death protein 1 (PD-1), lymphocyte-activation protein 3 (Lag-3), and TIGIT play an essential role in the prevention of autoimmune disorders by promoting tolerized responses." (PMID 30564191, 2018). "Additionally, the expression of LAG-3 has been shown to facilitate the immunomodulatory function of Tregs and NK/NKT cells in a variety of scenarios including autoimmunity and cancer." (PMID 28880895, 2017). "For example, LAG3 is a CD4 receptor homologue that by interfering with MHCII on APC upon antigen exposure inhibits the function and expansion of memory T cells decreasing IL-17 and increasing IL-10 secretions, this way preventing autoimmunity in mice." (PMID 27256343, 2016). "This intermediate resistance to suppression is consistent with the phenotype of LAG-3 KO mice, which show an initial lymphocyte expansion at birth, but which do not develop overt autoimmunity." (PMID 25372844, 2014). "In T cells, LAG3 is colocalized with T cell receptor/CD3 complex within immune synapses and inhibits TCR signaling, leading to impaired cell activation, proliferation, differentiation, and effector functions in the context of autoimmunity, infection, and tumor." (PMID 40359031, 2025). "Also, it is notable that a new phase I/II clinical trial (NCT03459222) has recently been opened to investigate the efficacy of triple targeting LAG-3, PD-1, and CTLA-4, which may be a novel combinatorial strategy in cancer treatment and autoimmune disorders." (PMID 30603054, 2018). "However, mice harboring the LAG3 K27E mutation, which abolishes FGL1 binding without affecting MHC binding, did not experience exacerbation of T1D, implying that FGL1 is not required for LAG3-mediated mitigation of autoimmunity, at least in the NOD model." (PMID 38556085, 2024). "It is possible, for example, that the LAG3 K27E mutation tested in NOD mice did not completely abrogate LAG3–FGL1 interactions under physiological conditions in vivo and that FGL1 may still contribute to limiting autoimmunity." (PMID 38556085, 2024). "Although neither LAG3 nor PD-1 single knockout animals succumb to autoimmunity, ablation of both results in multi-organ lymphocytic infiltration, and early death, reinforcing the notion that LAG3 and PD-1 may compensate each other in regulating T cell function." (PMID 29482595, 2018).
gastric cancer (69 papers, 2020 to 2026). A primary or metastatic malignant neoplasm involving the stomach. "Conversely, in gastric cancer, lymphoma, and colorectal cancer, high LAG3 expression has been associated with a favorable prognosis." (PMID 38277212, 2024). "Conversely, in EBV-positive and MLH1-defective gastric cancer LAG-3+ cell infiltration is strongly associated with inferior clinical outcomes." (PMID 36077354, 2022). "For instance, LAG3 was reported to be associated with poor OS in colorectal cancer and non-small cell lung cancer, whereas it was a favorable prognostic marker in gastric cancer." (PMID 36376922, 2022). "Additionally, gastric cancer and esophageal cancer were tightly linked to LAG3, which was thought to be a prospective therapeutic target for antitumor therapy." (PMID 37142949, 2023). "For gastric cancer, LAG-3 overexpression is actually associated with a favorable prognosis." (PMID 37509517, 2023). "LAG3 and its ligands are associated with the prognosis of gastric cancer." (PMID 35111155, 2021). "Furthermore, in advanced gastric cancer, a higher ratio of LAG3+CD4+/CD4+ T cells and LAG3+CD8+/CD8+ T cells is associated with better prognosis, although, at the invasive tumor margin, higher LAG3 expression is associated with better prognosis." (PMID 35111155, 2021). "High expression of LAG3 on tumor infiltrating lymphocytes and the presence of its soluble form (sLAG3) in the serum of patients has been associated with a better prognosis in some types of cancer, including hormone receptor positive breast cancer, gastric cancer, and colon cancer." (PMID 32861198, 2020). "The key regulatory role of LAG3+ TAMs in the progression of gastric cancer was explored by Chromatin Immunoprecipitation, dual luciferase reporter, cytokine array and subcutaneous xenograft models." (PMID 41923099, 2026). "LAG-3, an emerging immune checkpoint molecule, is often co-expressed with PD-1 in infiltrating lymphocytes of gastric cancer, and its high expression is frequently accompanied by upregulation of PD-L1 and CTLA-4, as well as higher TMB." (PMID 41228276, 2025). "In cancers such as TNBC and gastric cancer, elevated LAG-3 expression is associated with improved clinical outcomes, and higher levels of LAG-3+ TILs are associated with prolonged survival." (PMID 39660130, 2024). "The results indicated that elevated LAG-3 expression was associated with improved prognosis in patients with stage II and III gastric cancer." (PMID 39660130, 2024). "We further accessed the expression of B cells, CD4+ T cells, CD8+ T cells, macrophages, neutrophils, and immune checkpoints (CTLA4, LAG3, PD-1, and PD-L1) in gastric cancer tissues using IHC and mIHC staining and multispectral image analysis." (PMID 38887558, 2024). "Their findings collectively illustrated that LAG-3 is a potential independent prognostic biomarker for gastric cancer patients." (PMID 39660130, 2024). "used monochromatic and multicolor immunohistochemistry to measure cell-surface LAG-3 expression in patients with gastric cancer." (PMID 39660130, 2024). "Survival analysis using Kaplan-Meier demonstrated that patients with gastric cancer who exhibited positive LAG-3 expression at the invasive margin or central region tended to improve overall survival compared to individuals with negative expression." (PMID 39252941, 2024). "Existing studies have shown that elevated LAG3 expression is unfavorable for the immunotherapeutic response in gastric cancer patients." (PMID 39777330, 2024). "The CCL14 protein was related to tumor differentiation and tumor depth and positively correlated with the presentation of LAG3 and PD-L1 in gastric cancer cells." (PMID 38887558, 2024). "Several drug candidates targeting LAG-3 are currently in clinical trials for the treatment of chordoma, esophageal cancer, gastric cancer, and multiple myeloma." (PMID 39660130, 2024).
gastric cancer (continued). "In this study, five crucial immunophenotype‐related molecules (WARS, UBE2L6, GZMB, BATF2, and LAG‐3) in the TME are determined in five public gastric cancer (GC) datasets (n = 1426) and an in‐house sequencing dataset (n = 79)." (PMID 36998102, 2023). "In gastric cancer, the co-expression of PD-1 and LAG3 is indicative of improved PFS, and the co-expression of TIM3 and LAG3 is associated with better OS and PFS." (PMID 38041068, 2023). "Another research has previously reported increased survival rates among patients with locoregional gastric cancer carrying LAG3 rs3782735 AG and GG genotypes in the Japanese cohort." (PMID 37131179, 2023). "A cell experiment also demonstrated the strong cytotoxicity of anti-LAG3 inhibitors as single drugs or combined with anti-PD-1/PD-L1 immunotherapy on gastric cancer cells." (PMID 36042469, 2022). "In the present study, 95 of 102 cases were EBER-positive, and these patients displayed high LAG-3 expression, in line with the findings in a previous study of gastric cancer." (PMID 35140722, 2022). "Circulating soluble LAG-3 was a good prognostic marker in gastric cancer and positively correlated with CD8+ T cell frequency and secretion of IL-12 and IFN-γ in peripheral blood." (PMID 35154142, 2022). "The serum concentration of LAG-3 is a potential prognostic marker for gastric cancer, non-small-cell lung cancer, and hepatocellular carcinoma." (PMID 35565664, 2022). "Previous studies have analyzed the relationship between the LAG3 expression level and the diagnosis and prognosis of gastric cancer." (PMID 36042469, 2022). "In advanced gastric cancer, compared to low expression of LAG3, high expression of LAG3 and OX40 indicates better therapeutic effect of nivolumab." (PMID 35111155, 2021). "A prospective immunohistochemical analysis reported that LAG3 expression is 24.7% (21/85) and 23.6% (48/203) in gastric cancer and colorectal cancer, respectively." (PMID 32411209, 2020). "LAG3 expression has been reported to be upregulated in tumor-infiltrating lymphocytes (TILs) from a wide range of other cancers, such as hepatocellular carcinoma, gastric cancer, and hematologic malignancies." (PMID 38277212, 2024). "This may be associated with the positive correlation between the expression of LAG3 on the surface of T cells and the expression level of PD-1/PD-L1 in the immune microenvironment of esophageal cancer, gastric cancer, and other tumors." (PMID 36042469, 2022). "Increased LAG3 expression was also observed in patients undergoing gastric cancer surgery." (PMID 36042469, 2022). "In gastric cancer, LAG-3 expression is positively correlated with a better prognosis." (PMID 36077354, 2022). "In addition, high expression of LAG3 in the gastric mucosal immune microenvironment suggests poor prognosis of gastric cancer." (PMID 36042469, 2022). "In another study, combinatorial Tim-3/Lag-3/PD-1 blockade significantly improved antitumor immunity in gastric cancer cell-T cell coculture models, suggesting the therapeutic potential of combinatorial therapy in gastric cancer patients." (PMID 36159789, 2022). "First, the expression level of LAG3 in peripheral blood was shown to be closely associated with TNM stage, depth of invasion, and degree of histological differentiation of gastric cancer, revealing the LAG3 expression level as a promising biomarker for the diagnosis of gastric cancer." (PMID 36042469, 2022). "In addition, clinical studies have found that among patients receiving gastric cancer immunotherapy (nivolumab ± ipilimumab, nivolumab), patients with high expression of LAG3 in the gastric mucosal immune microenvironment have a better prognosis." (PMID 36042469, 2022). "In breast and gastric cancer, high levels of serum LAG-3 were correlated with improved prognosis." (PMID 34691076, 2021).